PCOLCE (procollagen C-endopeptidase enhancer)
Description:
Binds to the C-terminal propeptide of type I procollagen and enhances procollagen C-proteinase activity. C-terminal processed part of PCPE (CT-PCPE) may have an metalloproteinase inhibitory activity.
Synonyms: PCPE-1; PCPE1; PCPE
Tractability: Antibody: UniProt places it where antibodies can reach, with medium confidence; UniProt predicts a signal peptide or a membrane-spanning region; its Gene Ontology location is reachable by antibodies, with medium confidence.
Gene: Protein-coding gene on chromosome 7 (100,602,334 to 100,608,175, forward strand). Ensembl gene ENSG00000106333.
Subcellular location: Secreted
Subcellular location (Human Protein Atlas): Golgi apparatus; Vesicles; Predicted to be secreted
Pathways (Reactome):
Extracellular matrix organization: Collagen biosynthesis and modifying enzymes; Crosslinking of collagen fibrils
Gene Ontology:
Molecular function: collagen binding; heparin binding; peptidase activator activity; protein binding; extracellular matrix structural constituent
Biological process: collagen biosynthetic process; proteolysis
Cellular component: extracellular exosome; extracellular matrix; extracellular region; non-collagenous component of interstitial matrix
Genetic constraint (gnomAD): Loss-of-function variants: 30 observed, 37.88 expected, observed/expected ratio (o/e) 0.79, 90% interval 0.59 to 1.07. The upper end of that interval is the gene's LOEUF score, 1.07, which puts it in group 4 of 6, group 1 being the genes least tolerant of losing a copy. Missense variants: 546 observed, 538.61 expected, observed/expected ratio (o/e) 1.01, 90% interval 0.94 to 1.09. Synonymous variants: 237 observed, 233.07 expected, observed/expected ratio (o/e) 1.02, 90% interval 0.91 to 1.13.
Homologues: Orthologues: chimpanzee PCOLCE (99% identical), macaque PCOLCE (97% identical), dog PCOLCE (88% identical), pig PCOLCE (88% identical), rat Pcolce (83% identical), guinea pig PCOLCE (83% identical), mouse Pcolce (83% identical), rabbit PCOLCE (77% identical), zebrafish pcolceb (47% identical), zebrafish pcolcea (46% identical). Paralogues in human: PCOLCE2 (40% identical), CUBN (30% identical), CDCP2 (27% identical), CNTNAP4 (15% identical), CNTNAP5 (15% identical), F5 (14% identical), CNTNAP2 (14% identical), CNTNAP1 (14% identical), F8 (13% identical), NRP1 (13% identical), CNTNAP3 (13% identical), CNTNAP3B (13% identical), and 23 more.
Diseases named in the same sentence as PCOLCE in open-access papers:
PCOLCE is named in the same sentence as 35 diseases in open-access papers, as found by Europe PMC text mining. Sharing a sentence is not in itself a finding about the gene and the disease. The quoted sentences say what the papers report.
liver fibrosis (7 papers, 2016 to 2024). "PCOLCE (Procollagen C-Endopeptidase Enhancer) has been shown to be the strongest in its correlation with the liver fibrosis phenotype." (PMID 28740751, 2017). "Moreover, PCOLCE, the gene encoding PCPE-1, has been identified as one of the top predictive genes and most differentially expressed gene in experimental liver fibrosis in rat." (PMID 27458976, 2016). "Here, we identified the secreted-type pro-fibrotic protein, procollagen C-endopeptidase enhancer-1 (PCPE-1), as a brown adipose tissue (BAT)-derived adipokine that promotes liver fibrosis in a murine obesity-induced MASH model." (PMID 39160276, 2024).
osteosarcoma (7 papers, 2021 to 2024). A usually aggressive malignant bone-forming mesenchymal neoplasm, predominantly affecting adolescents and young adults. "PCOLCE was overexpressed in osteosarcoma and promoted lung metastasis via twist family bHLH transcription factor 1 (TWIST1)." (PMID 35036081, 2022). "RNA-seq analysis has shown the overexpression of PCOLCE in osteosarcoma tissues." (PMID 38534381, 2024). "Indeed, N-glycosylation of Procollagen C-proteinase enhancer protein (PCOLCE) is crucial for the development of lung metastasis in osteosarcoma." (PMID 38534381, 2024). "PCOLCE is upregulated by TWIST1 in osteosarcoma and promotes osteosarcoma metastasis to the lung." (PMID 37197432, 2023). "PCOLCE is a direct transcriptional target of TWIST1 and it is implicated in the regulation of collagen deposition during both early craniofacial development and in osteosarcoma, where it promotes tumor growth, cell migration, and invasion." (PMID 35022561, 2022). "Reducing PCOLCE expression could prevent the migration, invasion and lung metastasis of osteosarcoma cells." (PMID 35036081, 2022). "PCOLCE was up-regulated in osteosarcoma and promotes the distant metastasis." (PMID 35127724, 2021). "Additionally, it is indicated that PCOLCE (procollagen C-proteinase enhancer protein) acts a pivotal part in promoting the lung metastasis of osteosarcoma." (PMID 35155451, 2021).
gastric cancer (3 papers, 2020 to 2024). A primary or metastatic malignant neoplasm involving the stomach. "Another important discovery of our research is that PCOLCE expression is linked to multiple immune infiltration levels in gastric cancer." (PMID 33392251, 2020). "In order to better understand the potential mechanisms and relationship of PCOLCE expression in gastric cancer, we explored the association of the PCOLCE expression and clinical characteristics in gastric cancer patients with the Kaplan–Meier plotter databases." (PMID 33392251, 2020). "Therefore, it was conceivable that high PCOLCE expression was an independent risk factor and led to a poor prognosis in gastric cancer and ovarian cancer patients." (PMID 33392251, 2020). "Thus, we evaluated the associations of PCOLCE expression with immune infiltration levels in gastric cancer from the TIMER database." (PMID 33392251, 2020). "Although several studies have probed the role of PCOLCE in different cancers and can also be used as a prognostic marker for gastric cancer, little has been reported on the role of PCOLCE in glioma." (PMID 36882457, 2023). "We found that the high expression of PCOLCE is a poor prognostic factor in patients with gastric cancer." (PMID 33392251, 2020). "All the results above suggested that overexpression of PCOLCE indicated unfavorable prognosis in patients with gastric cancer." (PMID 33392251, 2020). "And the increased expression of PCOLCE mRNA was closely linked to shorter overall survival (OS), progress-free survival (PFS) in all gastric cancers." (PMID 33392251, 2020). "Our findings confirm the key role of PCOLCE in gastric cancer and provide the potential relationship and mechanism between PCOLCE and tumor-immune interaction." (PMID 33392251, 2020). "It was worth noting that the expression of PCOLCE had a significant impact on the prognosis of gastric cancer, ovarian cancer, hepatocellular carcinoma and bladder cancer." (PMID 33392251, 2020). "In this report, we revealed that high PCOLCE expression indicated poor prognosis in patients with gastric cancer." (PMID 33392251, 2020). "In summary, these findings suggest that PCOLCE plays an important role in the recruitment and regulation of immune infiltrating cells in gastric cancer." (PMID 33392251, 2020). "The exact biological role of PCOLCE was not yet clear and there were few reports study the correlation of PCOLCE gene expression level with the occurrence and development of gastric cancer." (PMID 33392251, 2020). "In this study, we comprehensively studied the expression of PCOLCE in patients with gastric cancer and its relationship with prognosis in databases such as Oncomine, Ualcan, and Kaplan–Meier plotter." (PMID 33392251, 2020). "Specifically, overexpression of PCOLCE mRNA was linked to worse OS and PFS in stage II to IV of gastric cancer patients (P<0.05) but has little influence on OS or PFS of patients in stage I (OS HR = 1.52, 95% CI = 0.55–4.22, P = 0.42; PFS HR = 0.47, 95% CI = 0.15–1.52, P = 0.20)." (PMID 33392251, 2020). "In this study, we used some bioinformatics network tools [UALCAN, Oncomine, and Kaplan–Meier (KM) plotter database] to evaluate the relationship between the expression of PCOLCE (procollagen C-protease enhancer protein) and the prognosis of patients with gastric cancer." (PMID 33392251, 2020). "Besides, PCOLCE expression displayed a tight correlation with infiltrating levels of macrophages and dendritic cells (DCs) in gastric cancer." (PMID 33392251, 2020). "Interestingly, the increased expression of PCOLCE could affect the prognosis of gastric cancer patients with lymph node metastasis, suggesting that the expression of PCOLCE could be used as an index to predict gastric tumor metastasis." (PMID 33392251, 2020).
gastric cancer (continued). "In addition, the high expression of PCOLCE also indicated that the prognosis of gastric cancer patients without distant metastasis is poor, suggesting that PCOLCE can be used as a predictor of patients with early gastric cancer." (PMID 33392251, 2020). "However, little is known about the role of PCOLCE in gastric cancer." (PMID 33392251, 2020). "The biological function of PCOLCE in tumor is not yet clear, and there are a few studies on the relationship between PCOLCE gene and the occurrence and development of gastric cancer." (PMID 33392251, 2020).
liver cancer (2 papers, 2017 to 2020). An epithelial or non-epithelial malignant neoplasm that arises from the liver. "In the current study, we have also identified few genes that are co-regulated with DAPK1, especially for SLC16A3, PCOLCE and ZBTB16, since the expression of these genes were dysregulated in liver cancer." (PMID 28740751, 2017). "DAPK1 expression was positively correlated with IRF2, IL7R, PCOLCE and ZBTB16, and negatively correlated with SLC16A3 in both liver cancer datasets." (PMID 28740751, 2017). "Among these genes, PCOLCE and ZBTB16 were significantly down-regulated, while SLC16A3 was significantly upregulated in liver cancer." (PMID 28740751, 2017).
melanoma (2 papers, 2021 to 2025). A malignant, usually aggressive tumor composed of atypical, neoplastic melanocytes. "PCOLCE was reported to be an important factor in the transition from telogen to anagen, and the expression of KDELR3 is associated with the development of melanocytes and the progression of melanoma." (PMID 35052373, 2021). "Many of these downregulated proteomic cargoes in melanoma sEVs, including collagens (COL1A1, COL3A1, COL6A1–A3, and COL14A1), matrix-associated proteoglycans (DCN, LUM, FMOD, OGN, and PRELP), and structural regulators (TNXB and PCOLCE), are key components of ECM organization and tensile strength." (PMID 41271007, 2025).
amyloid (1 paper, 2024). "BCAN, MDH1, PCOLCE and SELENBP1, to our knowledge, have not previously been implied in CAA/amyloid pathology." (PMID 38191511, 2024).
aneurysm (1 paper, 2022). Bulging or ballooning in an area of an artery secondary to arterial wall weakening. "PCOLCE, CORO1A, and FERMT3/KINDLIN3 in the combined networks suggest a role for collagen turnover and angiogenesis, platelet function, and integrin biology pathways also identified in the murine aneurysm proteomes." (PMID 35990960, 2022).
glioma (1 paper, 2023). A benign or malignant brain and spinal cord tumor that arises from glial cells (astrocytes, oligodendrocytes, ependymal cells). "Our study found that high PCOLCE expression is associated with poor prognosis in patients with glioma, which may be due to suppression of tumor-associated immune cells." (PMID 36882457, 2023). "Based on these findings, high expression of PCOLCE was identified as an independent prognostic factor for patients with gliomas." (PMID 36882457, 2023). "Compared to normal brain tissue, PCOLCE expression was increased in glioma and correlated with shorter overall survival (OS)." (PMID 36882457, 2023). "Kaplan–Meier curve survival analysis showed that high expression of PCOLCE significantly affects the prognosis of glioma patients.To confirm this result, univariate and multivariate Cox analyses were performed." (PMID 36882457, 2023). "PCOLCE is involved in the progression of many types of cancers; however, its role in glioma was unknown." (PMID 36882457, 2023). "PCOLCE was highly expressed in both glioma and GBM samples compared to normal samples (P < 0.0001)." (PMID 36882457, 2023). "Lastly, we did not investigate the role of PCOLCE in glioma subtypes, such as diffused midline and recurrent gliomas." (PMID 36882457, 2023).
joint disease (1 paper, 2019). "Biological inference prioritized notable DMRs associated with skin disease (SIGLEC14, JAM3, PCOLCE, RXRB), skin and/or joint disease (MBP, OSBPL5, SNORD115, HCG26), and joint disease (IL22, ELF5, PPP2R2D, PTPRN2, HCG26)." (PMID 30779748, 2019). "Although few DMRs exceeded a 10% change in methylation, it is noteworthy that many of those which did play roles in the pathogenesis of skin disease (SIGLEC14, JAM3, PCOLCE, RXRB, ELF5, IL22), joint disease (MBP, HCG26, IL22, PPP2R2D, PTPRN2) or are known to be imprinted (OSBPL5, SNORD115)." (PMID 30779748, 2019).
lymphoma (1 paper, 2020). A malignant (clonal) proliferation of B- lymphocytes or T- lymphocytes which involves the lymph nodes, bone marrow and/or extranodal sites. "The results showed that the expression of PCOLCE in brain and central nervous system, colorectal, esophagus, stomach, head and neck, lymphoma, pancreas, prostate, and sarcoma was higher than that in normal tissues." (PMID 33392251, 2020).
Obesity (1 paper, 2024). Accumulation of substantial excess body fat. "This study identifies procollagen C-endopeptidase enhancer-1 (PCPE-1) as an adipokine released from brown adipose tissue (BAT) upon dietary obesity." (PMID 39160276, 2024).
skin aging (1 paper, 2014). The gradual irreversible changes in structure of skin that occur as a result of the passage of time.. "Additionally, in the presence of MAAs, the UV-suppressed genes, procollagen C proteinase enhancer (PCOLCE) and elastin, which are related to skin aging, had increased expression levels equal to those in UV-mock treated cells." (PMID 25317535, 2014).
tumor (12 papers, 2016 to 2025). "Significantly, PCOLCE has been identified as an extracellular tumor-suppressing protein known to bind to APP, thus shedding light on its role in the observed effects." (PMID 38389836, 2024). "PCOLCE acted as an extracellular tumor-suppressing protein by interacting with amyloid precursor protein, a prognostic OS marker with poor survival." (PMID 36943734, 2023). "We found that PCOLCE expression was significantly correlated with patient age, tumor grade, histology, MGMT methylation levels, 1p19q co-deletion, and IDH mutation (P < 0.001) but not patient gender (P > 0.05)." (PMID 36882457, 2023). "Notably, the level of CALR transcripts was elevated in OS tissues, together with other tumor-suppressing proteins, including histone H4, and PCOLCE." (PMID 36943734, 2023). "Comparingtumor with corresponding control samples revealed 221 differentiallyexpressed proteins (FDR < 0.05) with FTL, PCOLCE, and RCN3 beingmost striking in tumor tissue." (PMID 40574313, 2025). "The unique interplay of proteins like PCOLCE, H4, PPIB, and ALDOA within LIV-treated MSC CM underscores their tumor-suppressive attributes." (PMID 38389836, 2024). "Alternatively, the selection of potent tumor-suppressing proteins such as CALR, ENO1, PCOLCE, etc. can be another option to construct a protein cocktail." (PMID 36943734, 2023). "We classified UM tumor cells into six distinct subclusters based on marker gene expression: C0 WSB1+ TCs, C1 EEF1A1+ TCs, C2 HSPB7+ TCs, C3 XIST+ TCs, C4 GNG11+ TCs, and C5 PCOLCE+ TCs." (PMID 39635521, 2024). "Together with the tumor-suppressing proteins such as CALR, ENO1, HSP, MSN, and UBC, which were enriched in tumor-suppressive CM, six recombinant proteins, such as HISTONE H4, PPIB, GJA1, CPE, S100A11, and PCOLCE, were identified as extracellular tumor-suppressing proteins." (PMID 36943734, 2023). "In addition to tumor-suppressing proteins that were enriched in CW-MSC CM such as CALR, we identified PCOLCE as a novel tumor-suppressing protein and proposed a regulatory axis of PCOLCE-APP for the treatment of OS." (PMID 36943734, 2023). "Procollagen C-endopeptidase enhancer 1 (PCPE-1) binds procollagen, potentiating its cleavage by specific proteinases, and might be involved in tumour growth." (PMID 29721183, 2018). "Hence, based on the overlapped upstream miRNAs and correlation analysis, we confirmed that the three key miRNAs (hsa-miR-124-3p, hsa-miR-26b-5p, and hsa-miR-192-5p) could regulate the four hub genes (CAV1, COL6A2, CSPG4, and PCOLCE) in GEM-resistance and tumor immune microenvironment." (PMID 35127724, 2021).
cancer (6 papers, 2016 to 2024). A tumor composed of atypical neoplastic, often pleomorphic cells that invade other tissues. "In this study, we examined the PCOLCE expression levels in different types of cancers using independent datasets in Oncomine and Ualcan databases." (PMID 33392251, 2020). "Here, we reported that variations in PCOLCE expression level correlate to prognosis in different types of cancer." (PMID 33392251, 2020). "Three proteins (CPE, S100A11, and PCOLCE) are reported tumorigenic in OS and/or other cancer." (PMID 36943734, 2023).
PCOLCE also shares sentences with these, for which no sentence is quoted: fibrosis (3 papers); steatosis (2); ameloblastoma (1); bladder cancer (1); bone disorder (1); chronic hepatitis B (1); Cirrhosis (1); emphysema (1); endocrine system disorder (1); gastric tumor (1); Hepatitis C (1); hepatocellular carcinoma (1); keloid (1); leiomyoma (1); liver dysfunction (1); liver steatosis (1); metabolic dysfunction-associated steatohepatitis (1); osteoporosis (1); ovarian carcinoma (1); Paget disease (1); sarcoma (1).